RHBG (Rh family B glycoprotein)
Description:
Ammonium transporter involved in the maintenance of acid-base homeostasis. Transports ammonium and its related derivative methylammonium across the basolateral plasma membrane of epithelial cells likely contributing to renal transepithelial ammonia transport and ammonia metabolism. May transport either NH4(+) or NH3 ammonia species predominantly mediating an electrogenic NH4(+) transport. May act as a CO2 channel providing for renal acid secretion.
Synonyms: SLC42A2
Tractability: Antibody: UniProt places it where antibodies can reach, with high confidence; its Gene Ontology location is reachable by antibodies, with high confidence; UniProt predicts a signal peptide or a membrane-spanning region.
Gene: Protein-coding gene on chromosome 1 (156,369,209 to 156,385,219, forward strand). Ensembl gene ENSG00000132677.
Subcellular location: Cell membrane; Basolateral cell membrane
Subcellular location (Human Protein Atlas): Nucleoplasm
Pathways (Reactome):
Transport of small molecules: Rhesus glycoproteins mediate ammonium transport
Gene Ontology:
Molecular function: ammonium channel activity; ankyrin binding; carbon dioxide transmembrane transporter activity
Biological process: ammonium transmembrane transport; transepithelial ammonium transport; ammonium homeostasis; carbon dioxide transmembrane transport
Cellular component: basolateral plasma membrane; plasma membrane; spectrin-associated cytoskeleton; membrane
Genetic constraint (gnomAD): Loss-of-function variants: 39 observed, 43.91 expected, observed/expected ratio (o/e) 0.89, 90% interval 0.69 to 1.16. The upper end of that interval is the gene's LOEUF score, 1.16, which puts it in group 5 of 6, group 1 being the genes least tolerant of losing a copy. Missense variants: 544 observed, 611.21 expected, observed/expected ratio (o/e) 0.89, 90% interval 0.83 to 0.95. Synonymous variants: 237 observed, 263.42 expected, observed/expected ratio (o/e) 0.9, 90% interval 0.81 to 1.
Homologues: Orthologues: chimpanzee RHBG (99% identical), macaque RHBG (98% identical), pig RHBG (89% identical), dog RHBG (87% identical), guinea pig RHBG (86% identical), rabbit RHBG (86% identical), rat Rhbg (85% identical), mouse Rhbg (84% identical), tropical clawed frog rhbg (63% identical), zebrafish rhbg (62% identical), Drosophila melanogaster Rh50 (45% identical), Caenorhabditis elegans rhr-1 (38% identical), and 1 more. Paralogues in human: RHCG (55% identical), RHAG (46% identical), RHCE (29% identical), RHD (29% identical).
Diseases named in the same sentence as RHBG in open-access papers:
RHBG is named in the same sentence as 12 diseases in open-access papers, as found by Europe PMC text mining. Sharing a sentence is not in itself a finding about the gene and the disease. The quoted sentences say what the papers report.
astrocytoma (1 paper, 2018). "However, they did not detect RhBG and RhCG mRNA in 1321N1 astrocytoma cells." (PMID 30134917, 2018).
bladder cancer (1 paper, 2022). "Then, 9 target genes that were differentially expressed between bladder cancer and normal samples were screened (FDR < 0.05), in which upregulated expression of RHBG, PAQR6, CLK2, KRTCAP2, FLAD1, HCN3 were correlated with bad survival of patients with bladder cancer." (PMID 36186809, 2022).
Chronic Renal Insufficiency (1 paper, 2026). "Single nucleotide polymorphisms of RhBG associated with CKD occurrence were identified using ancestry-stratified data from the Chronic Renal Insufficiency Cohort (CRIC) study." (PMID 41674104, 2026). "Here, we report six rare RhBG mutations associated with CKD, identified using data from the Chronic Renal Insufficiency Cohort (CRIC) study." (PMID 41674104, 2026).
colon adenocarcinoma (1 paper, 2015). "Moreover, similar TCF4 silencing experiments performed in SW480 colon adenocarcinoma cells also decreased RHBG, Axin2 and Cyclin D1 mRNA levels." (PMID 26029888, 2015).
colon cancer (1 paper, 2015). "We show that RHBG is expressed in the colon cancer SW480 cells bearing an APC mutation and that its expression is also dependent on TCF4/ β-catenin." (PMID 26029888, 2015). "Similarly, the RHBG expression revealed in SW480 colon cancer cells is dependent on β-catenin, further supporting the role of β-catenin signaling in RHBG regulation." (PMID 26029888, 2015).
hepatocellular carcinoma (1 paper, 2015). A malignant tumor that arises from hepatocytes. "Of note, RHBG appears overexpressed in human hepatocellular carcinoma bearing activating mutations in β-catenin, suggesting a correlation between Wnt/β-catenin signaling and human RHBG regulation." (PMID 26029888, 2015). "We show that RHBG is highly expressed in HepG2 hepatoma cells and relies on β-catenin signaling." (PMID 26029888, 2015). "The human RHBG gene was found to be overexpressed in a subset of hepatocellular carcinoma, however, the regulatory mechanisms involved remain unknown." (PMID 26029888, 2015).
cancer (1 paper, 2015). A tumor composed of atypical neoplastic, often pleomorphic cells that invade other tissues. "Taken together, our results indicate RHBG expression as a direct target of β-catenin regulation, a pathway frequently deregulated in many cancers and associated with tumorigenesis." (PMID 26029888, 2015). "We next tested whether the β-catenin signaling could be correlated with RHBG expression in another cancer cell line harboring β-catenin signaling activating mutations." (PMID 26029888, 2015). "Here, we sought to identify human cancer cell lines expressing the RHBG gene to study its expression regulation and address the potential direct influence of the Wnt/β-catenin signaling." (PMID 26029888, 2015). "In order to identify a cancer cell line that could be used to address the regulation of RHBG, we evaluated its expression levels in the HepG2 and Hep3B hepatoma cells." (PMID 26029888, 2015). "Our data support a direct role of β-catenin/TCF4 in the regulation of RHBG expression in this cell line, and further indicate that RHBG could serve as a direct reporter of the Wnt/β-catenin pathway in specific cancer cell contexts." (PMID 26029888, 2015). "Whether RhBG actively participates to cancer cell metabolism will require further investigation." (PMID 26029888, 2015).
RHBG also shares sentences with these, for which no sentence is quoted: breast carcinoma (1 paper); Cirrhosis (1); glioma (1); neuroblastoma (1); tumor (1).